PPM1D (protein phosphatase, Mg2+/Mn2+ dependent 1D)
Diseases named in the same sentence as PPM1D in open-access papers (continued):
Sharing a sentence is not in itself a finding about the gene and the disease.
glioma (continued). "Ubiquitous activation of mutant Ppm1d was modeled using the Meox2-Cre driver, and primary gliomas were modeled using the RCAS/tv-a system to introduce Cre and PDGFB co-drivers into Nestin-positive neural stem cells." (PMID 41394550, 2025). "We have generated mouse models of genetically engineered, PPM1D-driven DMG, including one that faithfully recapitulates endogenous PPM1D truncation as observed in human gliomas." (PMID 35105861, 2022). "GFP-positive sgPpm1dexon6 IUE brainstem tumors harbored truncations in exon 6 of Ppm1d and displayed histopathological traits of high-grade glioma." (PMID 35105861, 2022). "To further evaluate the role of PPM1D mutations in gliomagenesis, we first performed a comprehensive analysis of whole-genome sequences (WGS) of 131 pre-treatment pediatric high-grade gliomas (pHGGs)." (PMID 35105861, 2022). "Overall, these findings demonstrate that PPM1D mutations drive a unique pattern of global DNA methylation, distinct from that found in IDH1 mutant gliomas, which is associated with CpG island hypermethylation and NAPRT gene silencing." (PMID 31439867, 2019). "Overexpression of Wip1 is observed in human gliomas, and PPM1D silencing suppresses proliferation of human glioma cells." (PMID 28402943, 2017). "PPM1D silencing using lentivirus-mediated RNAi has been identified as a potential therapeutic approach for the treatment of human glioma." (PMID 25123458, 2014). "We hypothesized that truncated Ppm1d expression in neural stem cells, a putative lineage-of-origin for gliomas, in combination with additional oncogenic drivers may accelerate gliomagenesis." (PMID 41394550, 2025). "In addition, non-sense mutations in exon 6 of the PPM1D leading to production of enzymatically active, C-terminally truncated PPM1D protein have been reported in various cancer types including colon cancer and glioma." (PMID 39237765, 2024). "While expression of Pdgfra, histone K27M or Ppm1d mutations alone do not result in high-grade glioma formation, the combination of Pdgfra and histone K27M mutations together results in a partially penetrant phenotype." (PMID 35105861, 2022). "Within our DMG WGS cohort, we did not observe differences in the frequency of PPM1D mutations between pre- and post-treatment glioma samples (Fisher’s exact test, P = 1), suggesting a role in enhancing de novo glioma formation." (PMID 35105861, 2022). "To address this, we leveraged In-Utero Electroporation (IUE) to induce C’ terminal truncation of endogenous Ppm1d to evaluate whether this was sufficient to induce glioma formation." (PMID 35105861, 2022). "However, several clues point to possible additional functions of PPM1D truncation in glioma development." (PMID 35105861, 2022). "To test whether PPM1D phosphatase activity is required for accelerated glioma formation in our models, we performed IUE of H3.3K27M and PdgfraD842V plasmids along with a mutant form of PPM1Dtr (PPM1Dtr-D314A), that inactivates the phosphatase activity." (PMID 35105861, 2022). "We addressed this question by evaluating whether the exogenous expression of human truncated PPM1D (PPM1Dtr) was also sufficient to promote glioma formation in vivo." (PMID 35105861, 2022). "In this study, we investigate the oncogenic role of PPM1D, a protein phosphatase often found truncated in pediatric gliomas such as DIPG, and uncover a synthetic lethal interaction between PPM1D mutations and nicotinamide phosphoribosyltransferase (NAMPT) inhibition." (PMID 31439867, 2019). "Knockdown of PPM1D in lung cancer cells resulted in decreased cell proliferation and impaired colony formation ability, which are in line with a previous report showing that downregulation of PPM1D by RNAi inhibited proliferation of glioma cells." (PMID 25123458, 2014).
glioma (continued). "Although this study identified a significant prognostic role for it in elderly GBM, the underlying mechanisms by which PPM1D may impact the prognosis of gliomas have not been explored, which is a direction for further research." (PMID 37360159, 2023). "As only five PPM1D mutant tumors were present in this diverse cohort (5 of 45 total samples; 11%), the whole genome methylation profiling and analysis performed in this study was likely not sufficient to specifically identify differences in DNA methylation patterns in these PPM1D mutant gliomas." (PMID 31439867, 2019). "The exogenous expression of the human truncated PPM1d, which is found in pediatric high-grade gliomas, by IUE is sufficient to promote glioma formation in the mouse brain." (PMID 37762431, 2023). "A recent study showed that in high-grade pediatric gliomas such as DIPG, a protein phosphatase coined PPM1D is commonly truncated." (PMID 35814452, 2022). "The PPM1D protein domains that contribute to its oncogenic effects to enhance glioma formation have not been evaluated." (PMID 35105861, 2022). "Notably, PPM1D mutant cells are shown to be sensitive to NAMPT inhibitors in vitro and in vivo, within both engineered isogenic astrocytes and primary patient-derived model systems, suggesting the possible application of NAMPT inhibitors for the treatment of pediatric gliomas." (PMID 31439867, 2019).
ovarian carcinoma (22 papers, 2012 to 2025). A malignant neoplasm originating from the surface ovarian epithelium. "The initial identification of PPM1D mutations in the blood of ovarian cancer patients first postulated them as biomarkers for ovarian cancer; however, further insights have clarified their role as markers of CH." (PMID 39352380, 2024). "PPM1D variants have been associated with predisposition to breast and ovarian cancers along with MUTYH and CHEK2." (PMID 36555431, 2022). "In conclusion, we investigated somatic mosaic PPM1D mutations in patients with various cancers, including breast and ovarian cancers and found that all four patients bearing the truncating mutations had a history of cisplatin-based chemotherapy." (PMID 31242196, 2019). "In our study, the median age of the patients with PPM1D truncating variants was 60 (range, 52–82), which was a little higher than the age of patients with familial breast and ovarian cancer." (PMID 31242196, 2019). "Somatic mosaic mutations of PPM1D in the blood have been more frequently found in patients with various cancers including breast and ovarian cancers compared to control groups, raising concern that it has a possible role in cancer predisposition." (PMID 31242196, 2019). "Truncating mutations of PPM1D, resulting in overexpression, are frequently found in the blood of patients with breast or ovarian cancer." (PMID 31242196, 2019). "We investigated the frequency of the somatic mosaic PPM1D mutation, in patients with breast or ovarian cancer, which is suggested to be low and related to a history of cisplatin-based chemotherapy." (PMID 31242196, 2019). "Our NGS hereditary cancer panel analysis with blood revealed somatic mosaic mutations of PPM1D in four out of 965 patients with breast and/or ovarian cancer (0.41%)." (PMID 31242196, 2019). "Mosaic PPM1D truncating mutation, which is found in the germline DNA of a small population of breast or ovarian cancer patients, was recently determined to be a genetic risk factor for those cancers." (PMID 28852847, 2017). "Activating germline mutations in the PPM1D gene have recently been associated with predisposition to breast and ovarian cancer." (PMID 25658463, 2015). "Overexpression of PPM1D is associated with poor prognosis in patients with lung cancer and ovarian cancer." (PMID 23556002, 2013). "Then, Kaplan–Meier Plotter was applied to analyse the relationship between the mRNA expression of PPM1D and patient prognosis in overall ovarian carcinoma and serous-subtype ovarian carcinoma." (PMID 35538489, 2022). "It confirmed the observed association (p = 5.67 × 10−4, OR = 1.3; OR CI = 1.12–1.52)—suggesting that reported observations regarding PPM1D and breast and ovarian cancers are more general." (PMID 29263833, 2017). "We confirm a specific link between PPM1D and ovarian cancer, consistent with previous reports linking PPM1D to breast and ovarian cancer." (PMID 29263833, 2017). "Comparably less common than PPM1D amplifications are rare nonsense mutations in the exon 6 of PPM1D that result in expression of abnormally stable WIP1 and promote development of breast and ovary cancer." (PMID 26883108, 2016). "Overexpression of constitutively active Akt in chemosensitive ovarian carcinoma cells inhibited CDDP-induced PPM1D downregulation and significantly reduced CDDP sensitivity." (PMID 23050965, 2012).
ovarian carcinoma (continued). "Amplification of the genomic locus 17q23 coding for PPM1D or production of a highly stable and enzymatically active mutant of PPM1D have been reported in breast and ovarian cancer, therapy‐induced acute myeloid leukaemia (t‐AML) and other haematological malignancies." (PMID 37067201, 2024). "The mean age at diagnosis of the PPM1D truncating mutation carriers was 63.5 years (range, 52–82 years), and they did not have family history of breast or ovarian cancer." (PMID 31242196, 2019). "PPM1D stability was enhanced following protein synthesis inhibition in resistant ovarian carcinoma cells, which contain constitutively active Akt, but not in their sensitive counterparts in response to CDDP treatment." (PMID 23050965, 2012).
neuroblastoma (19 papers, 2008 to 2025). Neuroblastoma (NB) is the most common solid, extracranial childhood tumor. "WIP1 is encoded by PPM1D, located on chromosome 17q23.2, a chromosome segment frequently gained in neuroblastoma." (PMID 40253363, 2025). "Genetic analyses have shown the presence of unbalanced chromosome 17q gain in 90% of high-risk neuroblastomas, and high expression of PPM1D is associated with adverse patient outcome." (PMID 34885154, 2021). "High expression of PPM1D is correlated to poor prognosis, and genetic or pharmacologic inhibition of WIP1 suppresses neuroblastoma growth." (PMID 40253363, 2025). "To study the potential tumorigenic function of PPM1D/WIP1 in neuroblastoma and medulloblastoma, we next used genetic manipulation through the stable knockdown of short-hairpin RNA (shRNA) against PPM1D." (PMID 34885154, 2021). "PPM1D, GNA13, and STAT family genes – all on 17q and implicated in up to 70% of neuroblastomas – showed the strongest correlations of copy number and cytotoxicity to targeted inhibitors." (PMID 34722256, 2021). "Here, we show that the level of PPM1D expression correlates with chromosome 17q gain in medulloblastoma and neuroblastoma cells, and both medulloblastoma and neuroblastoma cells are highly dependent on PPM1D expression for survival." (PMID 34885154, 2021). "Overexpression of PPM1D is an important tumorigenic factor in medulloblastoma and neuroblastoma, as these tumor cells are highly dependent on high levels of PPM1D for their survival." (PMID 34885154, 2021). "Accordingly, we observed increased phosphorylation of DDR proteins and H2AX, enhancing the sensitivity to irradiation of PPM1D knockdown neuroblastoma cells." (PMID 34885154, 2021). "Similar potentiation of the cytotoxic effect of doxorubicin by WIP1 inhibition has recently been reported in neuroblastoma cells and in a colorectal carcinoma cells with a C-terminally truncated PPM1D." (PMID 26883108, 2016). "Chromosomal locus 17q23 carrying the PPM1D gene is commonly amplified in various human tumors including breast, ovarian and gastric cancer, neuroblastoma and lung adenocarcinoma." (PMID 26883108, 2016). "Neuroblastomas in particular have previously been shown to have 17q amplification, harboring the WIP1 (PPM1D) gene and associated with poor clinical outcome." (PMID 25658463, 2015). "Since WIP1 (PPM1D) is reported to be altered in neuroblastoma, we investigated if there was a relationship between the sensitivity of neuroblastoma cell lines and PPM1D copy number status." (PMID 25658463, 2015).
neuroblastoma (continued). "Having established that PPM1D-knockdown reduces tumor formation in mice and that gain of chromosome 17q harboring PPM1D is a strong prognostic factor for poor survival in both neuroblastoma and medulloblastoma, we next investigated the effects of compounds inhibiting WIP1 activity in both cancers." (PMID 34885154, 2021). "Besides breast and ovarian cancer, PPM1D copy numbers gain or overexpression at mRNA level were reported also in glioma, neuroblastoma, and medulloblastoma." (PMID 28439615, 2017). "Here, we focus on the role of PPM1D in neuroblastoma pathogenesis." (PMID 25658463, 2015). "PI3Kα inhibitor PIK-75 (78.9% cytotoxicity) stimulates anti-neuroblastoma activity by destabilizing MYCN and sensitizing tumor cells to anthracyclines, and indeed increased cytotoxicity with PIK-75 was associated with PPM1D and GNA13 gain, and DNMT3A, CBL, EED and ASXL2 loss." (PMID 34722256, 2021). "To functionally test the importance of PPM1D in neuroblastoma and medulloblastoma, we investigated the effects of genetic or pharmacological inhibition of WIP1 and demonstrated that blocking the expression or activity of WIP1 suppressed both neuroblastoma and medulloblastoma growth in vivo." (PMID 34885154, 2021).
medulloblastoma (17 papers, 2013 to 2023). A malignant, invasive embryonal neoplasm arising from the cerebellum. "The highest expression of PPM1D is observed in Group 3 and Group 4 as well as in metastatic medulloblastomas." (PMID 34885154, 2021). "Furthermore, high PPM1D expression has been reported to be correlated with poor prognosis in patients with pancreatic neuroendocrine tumors and medulloblastoma." (PMID 25009596, 2014). "Furthermore, the relative expression level of PPM1D mRNA was higher in medulloblastoma cell lines with 17q-gained aberrations (D283-MED, D458-MED and MEB-MED8A) compared to cell lines with normal 17q (DAOY, UW228-3 and PFSK-1), further demonstrating a gene-dosage effect on PPM1D mRNA expression." (PMID 34885154, 2021). "In cell lines of medulloblastoma origin, MDM2 showed the largest difference in dependency score with negative regulators PPM1D, USP7 and MDM4, ranked 6, 41 and 64, respectively." (PMID 34885154, 2021). "Additionally, studies in mice have shown that enhanced expression of PPM1D increases the onset of ERBB2-induced mammary gland tumors and also increases the incidence of SHH-driven medulloblastomas." (PMID 34885154, 2021).